CRP (C-reactive protein)
Diseases named in the same sentence as CRP in open-access papers (continued):
Sharing a sentence is not in itself a finding about the gene and the disease.
schizophrenia (continued). "A number of cross-sectional studies have demonstrated increased CRP levels in schizophrenia patients compared to controls, and longitudinal studies have demonstrated that higher CRP levels at baseline may increase the risk of schizophrenia at follow-up." (PMID 40724779, 2025). "However, the value of CRP level measurement as a means of ultimately reducing mortality risk in patients with schizophrenia remains to be determined." (PMID 41281897, 2025). "•C- reactive protein (CRP) was associated with mortality in schizophrenia." (PMID 41281897, 2025). "The estimated indirect effect of neuroinflammatory-specific polygenic risk for schizophrenia on the ganglion cell inner plexiform layer through the mediator CRP was −0.001, with a 95% bootstrap CI of −0.003 to −0.0002, suggesting a statistically significant partial mediation effect (P = 0.005)." (PMID 40365461, 2025). "In the case that CRP does serve a mediating role, this would suggest that neuroinflammatory processes, as indexed by CRP levels, could be a key biological pathway through which genetic risk factors for schizophrenia contribute to macular effects." (PMID 40365461, 2025). "This might explain our finding of a partial mediation effect of CRP, suggesting its mediating role alongside other potential candidates, in the association between neuroinflammatory-enriched polygenic risk scores for schizophrenia and retinal thickness." (PMID 40365461, 2025). "However, while observational data show a positive association between CRP and schizophrenia risk, Mendelian Randomization (MR) analyses indicate that genetically elevated CRP protects against schizophrenia risk." (PMID 40724779, 2025). "Furthermore, the outcome model showed a significant effect of CRP on ganglion cell inner plexiform layer thickness, after accounting for the same covariates, fasting time and neuroinflammatory polygenic risk for schizophrenia." (PMID 40365461, 2025). "Eleven factors including total dairy product, birth weight, calcium, CRP, circulating 25-hydroxyvitamin D, and UC positively linked with prostate cancer and coffee, selenium, vitamin E, schizophrenia, and T2D inversely associated with prostate cancer showed null causal associations by MR studies." (PMID 38489391, 2024). "CRP was previously reported for its association with aggressive behaviors and disordered personalities; Mendelian randomization analyses have shown a possible causal protective role of CRP toward schizophrenia and a potential risk-increasing effect on bipolar disorder." (PMID 37873776, 2023). "Our results also showed that CRP and C3 may be the independent risk factor positive symptoms in schizophrenia." (PMID 37520223, 2023). "Furthermore, a recent MR study has demonstrated that genetically proxied high levels of CRP significantly mitigate the risk of schizophrenia." (PMID 37600668, 2023). "Our goal was to search for associations between BDNF, CRP, IL-6 and clinical symptoms, cognitive and personal performance in patients with paranoid schizophrenia to try to identify specific subtypes of patients and search for their potential therapeutic targets." (PMID 35873262, 2022). "Evidence for elevated CRP levels in schizophrenia has a low risk of bias." (PMID 35546942, 2022). "An elevated CRP level was associated with cognitive impairment in schizophrenia." (PMID 35163141, 2022). "In subgroup analyses limited to the SNPs that were associated with CRP levels only, no outcome showed strong evidence for a causal effect except for schizophrenia which presented modest evidence for inverse associations with genetically determined higher CRP levels." (PMID 36376304, 2022). "In some studies, C-reactive protein levels were associated with schizophrenia aggression." (PMID 35502339, 2022). "CRP has been suggested as a biomarker for onset risk, as well as a risk factor for cardiovascular disease, MetS and increased nicotine dependence in smokers with schizophrenia." (PMID 35794221, 2022).
schizophrenia (continued). "Indeed, these studies have identified inflammatory drivers associated with schizophrenia, such as Vcam1, C-reactive protein (CRP), and various cytokines." (PMID 34741130, 2022). "Schizophrenia is associated with elevated levels of circulating C-reactive protein (CRP) and other inflammatory markers, but it is unclear whether these associations extend to psychotic symptoms occurring in adolescence in the general population." (PMID 33229033, 2021). "In addition, individuals with an elevated baseline CRP (due to any cause such as an autoimmune disease) level had a six to eleven times greater chance of developing schizophrenia late in their adult life." (PMID 34884840, 2021). "Additionally, a recent systematic review recorded elevated CRP levels to be notably associated with positive symptoms of acute psychosis seen in schizophrenia." (PMID 34884840, 2021). "Schizophrenia had evidence from independent studies and sensitivity analysis (weighted median and inverse variant weighted estimate), but this was not supported by MR Egger analysis and the sensitivity analysis using only CRP gene SNPs (P = 0.04)." (PMID 32978716, 2021). "Additionally, higher CRP levels were measured in patients suffering from schizophrenia, possibly linked to inflammation in the pathogenesis of schizophrenia." (PMID 33673378, 2021). "Similarly, elevated levels of CXCL8 (IL8), and TNFα as well as the acute phase protein C-reactive protein (CRP) in maternal serum are linked to an increased risk of schizophrenia in offspring." (PMID 34858132, 2021). "A modest rise in CRP levels was associated with schizophrenia in comparison to healthy controls." (PMID 34884840, 2021). "Both age45–47 and sex47,48 are separately associated with schizophrenia risk and levels of CRP." (PMID 34050185, 2021). "However, it is important to note that findings of individual cross-sectional studies conducted to investigate the association of CRP and psychotic symptoms manifesting in schizophrenia show considerable heterogeneity and variable conclusions." (PMID 34884840, 2021). "However, Mendelian randomization (MR) studies on CRP and risk of developing schizophrenia have mostly shown CRP to have a protective causal effect." (PMID 34884840, 2021). "While an increased CRP level is noted, it is unclear whether this is an effect of schizophrenia or it is directly involved in the pathogenic mechanism behind it." (PMID 34884840, 2021). "Previous research demonstrated that T. gondii infection causes neural damage and reactive tissue repair in mice similar to those observed in the brain of schizophrenia patients, and that both T. gondii infections in mice and schizophrenia are associated with elevated levels of CRP and VCAM-1." (PMID 33602170, 2021). "However, it is possible that genetic predisposition for decreased CRP levels/activity increase susceptibility to infection leading to increased schizophrenia risk through immune, neurodevelopmental and/or other mechanisms." (PMID 33684738, 2021). "Increased CRP has also been recently linked with a significant decline in multiple cognitive domains, including working memory and learning ability, in individuals of all ages suffering from schizophrenia." (PMID 34884840, 2021). "The role of CRP in the causality of schizophrenia has been a subject of interest for many years." (PMID 34884840, 2021). "Rs1880241, a top SNP of a clump significantly interacting with childhood adversities on lifetime suicide attempts has been found to be related to level of circulating CRP in a study revealing a protective effect of CRP on schizophrenia and a risk effect of CRP on bipolar disorder." (PMID 34777050, 2021). "However, it is also possible that genetic predisposition for T2DM or schizophrenia influences CRP via mechanisms other than IL-6." (PMID 32828613, 2020).
schizophrenia (continued). "Moreover, population-based cohort studies have observed that elevated levels of serum CRP and IL-6 in childhood are associated with increased risk of psychotic experience and schizophrenia in adulthood." (PMID 29743584, 2019). "Additionally, elevated blood CRP concentration was associated with resistance to treatment in schizophrenia patients." (PMID 30178287, 2019). "Whether, indeed, the nature of association between schizophrenia and inflammatory markers varies depending on stage of development requires examination using repeat measurements of CRP and other inflammatory markers from the same individuals over time." (PMID 31563954, 2019). "Therefore, it is possible that inflammatory overactivity seen in adult schizophrenia patients is in fact influenced by genetically driven deficits in CRP levels/activity in early life that predispose these individuals to infection." (PMID 31563954, 2019). "CRP levels have been associated with cognitive impairment in patients with schizophrenia." (PMID 30394240, 2019). "While there are a number of MR studies testing the association of schizophrenia with individual inflammatory markers, and with certain cardiometabolic risk factors, this study included a broad range of cardiometabolic markers along with CRP." (PMID 31563954, 2019). "Similarly, higher levels of CRP are associated with a lower cognitive function in patients with schizophrenia." (PMID 29622048, 2019). "A study from 2016 surprisingly found a protective role of genetically elevated CRP levels on the risk for schizophrenia, as well as weak (nominally significant) evidence for a risk increasing effect on bipolar disorder as well as a range of other somatic traits." (PMID 28847336, 2018). "Whilst a small number of studies have shown an association between elevated CRP and decreased structural brain volume in healthy older adults, there have been no studies to date assessing the potential link between CRP and cortical thickness in schizophrenia." (PMID 30364161, 2018). "Interestingly, elevated CRP levels in pregnant women were associated with a higher risk of the offspring developing schizophrenia." (PMID 29434554, 2018). "The impaired 6MWD (6-minute-walk distance, difference between actual and predicted distance) and dyspnea were correlated to CRP and an association between impaired physical functioning and elevated levels of CRP in patients suffering from schizophrenia emerged." (PMID 29434554, 2018). "Some authors have gone so far as to regard CRP as a causative component of schizophrenia alongside other inflammatory molecules such as IL-8 and TNF-alpha, which may alter neurodevelopment." (PMID 29404313, 2017). "We found that blockade of interleukin-6 effects and low C-reactive protein levels might increase schizophrenia risk, possibly due to increased susceptibility to early life infection." (PMID 29094161, 2017). "Serum CRP levels at age 15/16 years were associated with risk of schizophrenia by age 27 years." (PMID 27622678, 2017). "Based on the hypothesized link between inflammation and schizophrenia, a few studies have investigated the association between plasma CRP and psychotic symptoms in schizophrenia." (PMID 29404313, 2017). "Adolescent CRP was associated with subsequent schizophrenia." (PMID 27622678, 2017). "Similarly, another population-based longitudinal study from Denmark has reported an increased risk of late- or very-late-onset schizophrenia in participants with higher serum CRP at baseline." (PMID 27622678, 2017). "Some studies of CRP and symptom severity in schizophrenia have suggested that CRP levels rise during acute psychotic episodes and that higher CRP levels are associated with heightened severity of psychosis and with exacerbation of negative symptoms and general psychopathology." (PMID 29404313, 2017). "We hypothesised that higher CRP levels in adolescence would be associated with greater risk for schizophrenia in adulthood." (PMID 27622678, 2017).
schizophrenia (continued). "However, it is possible that only exposure to IL-6 and CRP in a specific window of time (eg, early life) affects schizophrenia risk." (PMID 29094161, 2017). "Mechanisms underlying the association of blockade of IL-6 classic signaling and lower CRP levels with increased risk of schizophrenia are unknown." (PMID 29094161, 2017). "Following comments made by the reviewers, we explored the possible underlying pathways that may explain the potential protective causal association between CRP and schizophrenia." (PMID 27327646, 2016). "In a follow-up analysis using the individual-level PGC data, we found that a GRS incorporating the same 18 CRP SNPs used to construct the GRSGWAS was again significantly associated with a lower risk of schizophrenia (OR 0.96 [95% CI 0.94–0.98]; p < 1.72 × 10−6)." (PMID 27327646, 2016). "In brief, our results show that pathways associated with the interferon response are significantly enriched amongst genes harbored by CRP loci and their associated expression quantitative trait loci (eQTLs) and that there are differentially expressed genes between schizophrenia cases and controls." (PMID 27327646, 2016). "In contrast, others have previously shown that CRP levels are significantly elevated in patients with schizophrenia, with a recent meta-analysis concluding that the association between elevated CRP and schizophrenia is indeed robust." (PMID 27327646, 2016). "Our finding may also point out potential biases in previous studies regarding the causes of elevated CRP levels in patients with schizophrenia, such as reverse causality and/or pleiotropic effects within chosen instruments." (PMID 27327646, 2016). "The aim of this study was to assess the influence of serum interleukin-6 (IL-6) level together with the polymorphism in its gene (IL6 -174G/C) and high sensitivity C-reactive protein (hsCRP) levels on clinical manifestation and cognition in schizophrenia patients." (PMID 25214388, 2015). "The influence of the immune system deregulation on the risk of schizophrenia has been reported for years now; however, the association between CRP and IL-6 with schizophrenia course and symptomatology, as well as with cognitive functioning has not been shown so far." (PMID 25214388, 2015). "A literature review did not identify any studies that explored the association between CRP and perceived family support and further examined whether this association differed along the BMI spectrum in a sample of outpatients with schizophrenia, leaving a knowledge gap that we sought to address." (PMID 40724779, 2025). "It shows that while increased CRP levels are clearly associated with cognitive impairment in schizophrenia, the correlation’s comparatively small practical significance implies that inflammation may not have a significant effect on cognitive dysfunction in the majority of schizophrenia patients." (PMID 39273641, 2024). "Nevertheless, the precise underlying mechanism connecting CRP and schizophrenia remains unclear." (PMID 37600668, 2023). "Also, maternal inflammation may play a significant role in the offspring’s schizophrenia, and increased maternal CRP has been significantly associated with the condition in their offspring." (PMID 37873776, 2023). "Besides, CRP levels have been associated with a risk of increased positive symptoms, cognitive impairment, microbiota disturbance, and metabolic syndrome in subjects with schizophrenia." (PMID 35546942, 2022). "Indeed, elevated cytokine transcription and plasma CRP in our patient cohort is associated with worse psychiatric and cognitive symptoms, strengthening the contention that even minor changes in cytokine transcription clinically relevant in schizophrenia." (PMID 35027554, 2022).
schizophrenia (continued). "In schizophrenia, another complex neuropsychiatric disorder sharing common genetic variation, and brain transcriptional dysregulation with autism, genetic loci associated with high circulating levels of CRP have been found protective in Mendelian randomization studies." (PMID 35393396, 2022). "Interestingly, however, MR findings have reported that genetically predicted CRP may have a protective effect on schizophrenia, with authors positing that a genetically attenuated ability to produce CRP may predispose to more insidious and chronic infections." (PMID 33711016, 2021). "This would support the potential role of CRP in the pathophysiology of schizophrenia, Moreover, studies based on cell culture indicate that CRP can induce a pro-inflammatory state in microglia, thus suggesting that CRP may be linked to neuro- inflammation in the central nervous system." (PMID 34465310, 2021). "However, other studies have reported an association between CRP levels and schizophrenia severity." (PMID 32061259, 2020). "By contrast, the (protective) apparent causal influence of CRP on schizophrenia is much more consistent between the CRP variant and all other instruments, indicating that whether a SNP exhibits horizontal pleiotropy is dependent on the causal question being asked." (PMID 29771313, 2018). "Although, cross sectional survey in the general population indicates a positive relationship between plasma CRP levels and Framingham 10-year Relative Risk score, the exact relationship between Framingham relative risk and CRP levels in schizophrenia remains unclear." (PMID 28396623, 2017). "The inflammatory biomarkers most frequently associated with CT are CRP, IL-1β, IL-6, and TNF-α, parameters which have also been found to be elevated in schizophrenia." (PMID 41049865, 2025). "Studies have shown that certain blood-based biomarkers, such as CRP and CD33, are causally linked to various psychiatric disorders, including schizophrenia, Alzheimer’s disease, and Parkinson’s disease." (PMID 39859234, 2025). "Age, smoking habit, BMI and IL-6 levels, medication time, elevated CRP levels, and exercise habit were the influencing factors for the development of MS in schizophrenia." (PMID 41450839, 2025). "In line with this consideration, several studies in different cultural and ethnic groups found significantly higher CRP levels in patients with schizophrenia compared to healthy control subjects, especially in those treated with antipsychotic medication." (PMID 40980040, 2025). "Numerous previous studies have investigated the relationship between CRP levels and schizophrenia and have come to contradictory conclusions." (PMID 40980040, 2025). "Elevated CRP concentrations and systemic inflammation observed in patients with schizophrenia support a model in which HERV-W expression bridges immune activation with neuronal dysfunction, even in the absence of active infection." (PMID 40806558, 2025). "Elevated mean CRP levels and reduced vitamin D concentrations were commonly reported in schizophrenia patients, in contrast to the matched controls." (PMID 40867540, 2025). "Inflammation, with increased levels of immune markers including CRP, is well established in schizophrenia." (PMID 41281897, 2025). "Studies highlight the important role of inflammation in the pathophysiology of schizophrenia, indicating elevated C-reactive protein (CRP) and cytokine levels (e.g., TNF-alpha, IL-6, and IL-8) in this disease." (PMID 40804390, 2025). "Contemporary scientific evidence implicates inflammatory processes in the pathogenesis of schizophrenia, with C-reactive protein (CRP) representing one of the most frequently investigated biomarkers for systemic inflammation." (PMID 40724779, 2025). "According to a meta-analysis of 50 studies involving patients with schizophrenia, CRP levels were higher than in controls, with a further increase during acute phases." (PMID 41281897, 2025).